TMPRSS4 (transmembrane serine protease 4)
Description:
Plasma membrane-anchored serine protease that directly induces processing of pro-uPA/PLAU into the active form through proteolytic activity. Seems to be capable of activating ENaC (By similarity). (Microbial infection) In gut epithelial cells, facilitates human coronavirus SARS-CoV-2 infection through, at least, the cleavage of coronavirus spike glycoproteins which activates the glycoprotein for host cell entry.
Synonyms: CAPH2; MT-SP2; TMPRSS3; CAP2
Tractability: Antibody: UniProt places it where antibodies can reach, with high confidence; UniProt predicts a signal peptide or a membrane-spanning region; its Gene Ontology location is reachable by antibodies, with medium confidence. PROTAC: a small molecule that binds it is known.
Target class: Enzyme; Protease; Serine protease
Gene: Protein-coding gene on chromosome 11 (118,077,012 to 118,125,510, forward strand). Ensembl gene ENSG00000137648.
Subcellular location: Cell membrane; Secreted (Transmembrane protease serine 4 catalytic chain)
Gene Ontology:
Molecular function: protein binding; serine-type peptidase activity; serine-type endopeptidase activity
Biological process: negative regulation of growth rate; positive regulation of viral entry into host cell; protein processing; proteolysis; regulation of gene expression
Cellular component: extracellular region; secretory granule; membrane; plasma membrane
Genetic constraint (gnomAD): Loss-of-function variants: 42 observed, 57.78 expected, observed/expected ratio (o/e) 0.73, 90% interval 0.57 to 0.94. The upper end of that interval is the gene's LOEUF score, 0.94, which puts it in group 3 of 6, group 1 being the genes least tolerant of losing a copy. Missense variants: 524 observed, 560.39 expected, observed/expected ratio (o/e) 0.94, 90% interval 0.87 to 1. Synonymous variants: 199 observed, 213.43 expected, observed/expected ratio (o/e) 0.93, 90% interval 0.83 to 1.05.
Homologues: Orthologues: chimpanzee TMPRSS4 (98% identical), macaque TMPRSS4 (96% identical), dog TMPRSS4 (82% identical), pig TMPRSS4 (80% identical), mouse Tmprss4 (76% identical), rabbit TMPRSS4 (76% identical), rat Tmprss4 (74% identical), guinea pig TMPRSS4 (73% identical), Drosophila melanogaster CG32808 (21% identical), Drosophila melanogaster CG3916 (19% identical), Drosophila melanogaster Phae2 (19% identical), Drosophila melanogaster CG12256 (19% identical), and 7 more. Paralogues in human: KLK11 (19% identical), KLK8 (19% identical), KLK2 (18% identical), KLK5 (18% identical), KLK14 (18% identical), KLK7 (18% identical), KLK12 (18% identical), KLK1 (17% identical), KLK3 (17% identical), KLK4 (16% identical), PRSS54 (16% identical), PRSS58 (13% identical).
Diseases named in the same sentence as TMPRSS4 in open-access papers:
TMPRSS4 is named in the same sentence as 67 diseases in open-access papers, as found by Europe PMC text mining. Sharing a sentence is not in itself a finding about the gene and the disease. The quoted sentences say what the papers report.
lung carcinoma (18 papers, 2011 to 2024). "Elevated TMPRSS4 expression is associated with poor prognosis in non–small cell lung cancer with squamous cell histology, triple-negative breast cancer, cervical cancer, gastric cancer, colon cancer, and prostate cancer." (PMID 34809669, 2021). "In this study, we explored the therapeutic potential of IMD-0354 and KRT1853 against TMPRSS4-expressing prostate, colon, and lung cancer cells and evaluated the underlying mechanism of anti-tumor activity." (PMID 31292507, 2019). "As TMPRSS4 had been linked to tumour development, we decided to study the role of this protein in lung cancer." (PMID 22067904, 2011). "Moreover, miR-149-3p negatively regulated TMPRSS4, reducing malignancy-associated characteristics of lung cancer cells and further improving their DDP sensitivity." (PMID 39388706, 2024). "Importantly, overexpression of TMPRSS4 in lung cancer cells is linked to increased resistance to DDP and other standard chemotherapeutic agents." (PMID 39388706, 2024). "Targeting the miR-149-3p/TMPRSS4 axis shows promise as a therapeutic strategy to overcome chemotherapy resistance in lung cancer patients." (PMID 39388706, 2024). "Collectively, these results demonstrate that excessive TMPRSS4 enhances the resistance of lung cancer cells to DDP." (PMID 39388706, 2024). "TMPRSS4 expression was further reduced, suggesting that miR-149-3p inhibited lung cancer progression and increased DDP sensitivity by negatively regulating TMPRSS4." (PMID 39388706, 2024). "In conclusion, miR-149-3p suppresses the aggressive progression of lung cancer by directly downregulating TMPRSS4 and enhances the responsiveness of lung cancer cells to DDP." (PMID 39388706, 2024). "In lung cancer tissues and cells, miR-149-3p expression was reduced, while TMPRSS4 expression was elevated." (PMID 39388706, 2024). "As demonstrated in other studies, downregulation of TMPRSS4 increases lung cancer cells’ sensitivity to chemotherapeutic drugs." (PMID 39388706, 2024). "In colon, prostate, and lung cancer cells, TMPRSS4 promotes the downregulation of E-cadherin, which is often accompanied by morphological changes and actin rearrangement, leading to EMT events and cancer cell invasion." (PMID 37009799, 2023). "TMPRSS4 expression in NSCLC samples correlates negatively with that of tissue factor pathway inhibitor 2 (TFPI-2), and TFPI-2 partially inhibits transcription of TMPRSS4, leading to reduced lung cancer cell growth." (PMID 37009799, 2023). "The knockdown of TMPRSS4 in lung cancer cells induced the downregulation of thymidylate synthetase (TS)." (PMID 34379296, 2022). "Consistent with our findings, a recent study showed that TMPRSS4 induces cancer stem–like properties in lung cancer cells and correlates with ALDH expression in NSCLC patients." (PMID 34809669, 2021). "Elevated expression of TMPRSS4 correlates with poor prognosis in colorectal cancer, gastric cancer, prostate cancer, non–small cell lung cancer, and other cancers." (PMID 34809669, 2021). "IMD-0354 and KRT1853 inhibited cancer cell invasion, migration, and proliferation in TMPRSS4-expressing prostate, colon, and lung cancer cells." (PMID 31292507, 2019). "Our first goal was to identify genes that were consistently correlated with TMPRSS4 expression and differentially expressed in lung cancer patients." (PMID 31659178, 2019). "Then, using the combination 50/20 ng DNA, we quantified by ddPCR a panel of 46 lung cancer cell lines in which we previously determined the methylation status of TMPRSS4 by 450k methylation arrays." (PMID 31817025, 2019). "For instance, the protein-coding genes CD36 and TMPRSS4 were already identified as potential therapeutic targets of lung cancer, while TMPRSS4 can induce cancer stem cell-like properties in lung cancer." (PMID 30453959, 2018). "We previously observed that TMPRSS4 is required for NCI-H322 lung cancer cell proliferation, which involves modulation of cell cycle factors." (PMID 27385093, 2016).
lung carcinoma (continued). "TMPRSS4 promotes invasion, migration and metastasis of colorectal and lung cancer cells by facilitating an EMT." (PMID 26993610, 2016). "We also reported that TMPRSS4 induces invasion of prostate and lung cancer cells through uPA gene expression, which involves AP-1 activation." (PMID 27385093, 2016). "TMPRSS4 is necessary and sufficient for the human lung cancer cell line NCI-H322, the colon adenocarcinoma cell line Colo205, and the colorectal cancer cell line HCT15 to accomplish migration and invasion." (PMID 23922976, 2013). "TMPRSS4 expression was also evaluated in lung cancer cell lines, which are commonly used in experimental tumor models to study lung tumor biology and test potential therapeutic agents." (PMID 22692880, 2012). "Using human lung cancer cell lines and tumor xenograft models, we also investigated the role of hypoxia in modulation of TMPRSS4 protein expression in the tumor microenvironment." (PMID 22692880, 2012). "When cell lysates were generated and analyzed by immunoblotting, only 2 cell lines stained positive for TMPRSS4 protein, the A549 lung cancer and MCF7 breast cancer lines." (PMID 22692880, 2012). "TMPRSS4 qPCR was performed on 16 lung cancer lines and variable numbers of TMPRSS4 transcripts were detected in 6 of 16 lung cancer lines." (PMID 22692880, 2012). "The need for identification of novel biomarkers and therapeutic targets for a more effective management of lung cancer led us to investigate TMPRSS4, a protease reported to promote tumour growth and metastasis." (PMID 22067904, 2011). "We show here first evidence that TMPRSS4 is highly expressed in lung cancer cell lines and patients, and that such expression is significantly associated with poor prognosis in the case of SCC histology." (PMID 22067904, 2011). "The potential use of TMPRSS4 as a biomarker for lung cancer detection or as a predictor of patient's outcome warrants further investigation." (PMID 22067904, 2011). "Analysis of the expression of TMPRSS4 mRNA levels in 34 lung cancer cell lines revealed that the majority of positive cells corresponded to AC histology." (PMID 22067904, 2011). "However, the specific mechanisms by which TMPRSS4 mediates DDP resistance in lung cancer cells remain insufficiently studied." (PMID 39388706, 2024). "This is achieved by specifically silencing TMPRSS4, a gene that may promote lung cancer development." (PMID 39388706, 2024). "Developing drugs that target miR-149-3p or TMPRSS4 could offer an effective approach to halting lung cancer metastasis and improving patient outcomes." (PMID 39388706, 2024). "Furthermore, TMPRSS4 upregulates transcription of the uPA gene in prostate and lung cancer cells by activating AP-1 and SP1/3 in a MAPK (mainly JNK)-dependent manner." (PMID 37009799, 2023). "Our finding on the expression of ACE2 and TMPRSS4 in lung cells enriched with malignant (adenocarcinoma) features may have implications for the management of COVID-19 in lung cancer, and clinical studies are warranted to explore this conjecture." (PMID 33809063, 2021). "Additionally, TMPRSS4 plays an influential role in radiosensitivity and chemosensitivity by disrupting cell cycle and apoptosis in lung cancer and triple-negative breast cancer." (PMID 33816264, 2021). "In lung cancer, TMPRSS4 promotes cell growth, and imparts drug resistance to chemotherapy." (PMID 33816264, 2021). "We next examined TMPRSS4 message in human lung cancer cell lines in culture." (PMID 22692880, 2012). "Primary human lung carcinoma samples were used to determine whether expression of TMPRSS4 protein coincided with hypoxic regions within the tumor mass." (PMID 22692880, 2012). "We next investigated whether TMPRSS4 would modify unidirectional cell migration in the lung cancer cells." (PMID 22067904, 2011).
lung carcinoma (continued). "Furthermore, in an in vivo model of lung cancer metastasis we show that inhibition of TMPRSS4 in luciferase-expressing H358 cells results in a decline in luminometric signals in the lungs." (PMID 22067904, 2011). "In all, 34 lung cancer cell lines were used to evaluate the TMPRSS4 expression." (PMID 22067904, 2011). "In-vivo experiments were performed to determine the role of TMPRSS4 in lung cancer development." (PMID 22067904, 2011). "Our results demonstrate that TMPRSS4 has a role in the lung cancer development." (PMID 22067904, 2011). "All these data support our hypothesis that TMPRSS4 has an important role in lung cancer, promoting cell proliferation, tumour growth and invasion." (PMID 22067904, 2011). "Finally, miR-149-3p and/or TMPRSS4 were overexpressed to observe changes in lung cancer cells, particularly DDP-resistant cells, to clarify the roles of miR-149-3p and TMPRSS4 in modulating DDP resistance in lung cancer, providing further insight for clinical treatment." (PMID 39388706, 2024). "In order to ascertain the possible cause of TMPRSS4 overexpression in lung cancer patients, we evaluated through bioinformatic analyses using public databases (COSMIC, CCLE, IGDB.NSCLC) possible genetic alterations (gene amplification, mutations, rearrangements) of TMPRSS4 in NSCLC." (PMID 26989022, 2016). "Therefore, TMPRSS4 participates in the lung cancer cell migration." (PMID 22067904, 2011). "Previously, we reported that TMPRSS4 induces EMT and invasion of colon, prostate, and lung cancer cells." (PMID 34809669, 2021). "Previous experiments in vitro and in vivo led us to demonstrate that TMPRSS4 enhances tumor growth and metastasis, and confers both epithelial to mesenchymal transition (EMT) and cancer stem cell (CSC) features in lung cancer cells." (PMID 31659178, 2019). "We previously showed that TMPRSS4 enhances EMT and invasion of colon, prostate, and lung cancer cells." (PMID 31292507, 2019). "The present study reports the novel finding that TMPRSS4 is highly overexpressed in NSCLC and has a role in lung cancer development." (PMID 22067904, 2011). "LSR may also activate the SARS−CoV−2 S proteins and increase the viral infection of lung cancer cells, along with host co-receptors that might be involved in cell infection, such as NETO2, GRP87, and transmembrane protease serine 4 (TMPRSS4)." (PMID 39228892, 2024). "As shown in the GEPIA database, TMPRSS4 expression was higher in lung cancer tissues compared to normal tissues." (PMID 39388706, 2024). "TMPRSS4 protein and mRNA levels, as assessed by Western blot and qRT-PCR, were consistent with the GEPIA database findings, showing that TMPRSS4 is highly expressed in lung cancer tissues and cells." (PMID 39388706, 2024). "In addition, overexpression of TMPRSS4 confers EMT features and CSC-like properties on lung cancer cells, accompanied by enhanced tumorigenicity in vivo." (PMID 37009799, 2023). "In addition, TMPRSS4 interacts with the uPA receptor (uPAR/CD87) to activate the JNK, ERK, and c-Src signaling pathways in prostate and lung cancer cells." (PMID 37009799, 2023). "We addressed whether the expression of TMPRSS4 and DDR1 would be mutually regulated in lung cancer cells." (PMID 31659178, 2019). "The H358 and H596 lung cancer cell lines were selected for these studies as they express high levels of TMPRSS4 transcripts but no detectable protein." (PMID 22692880, 2012). "On the other hand, we did not observe TMPRSS4-, SLUG-, or TWIST1-mediated upregulation of SOX2, in lung cancer cells (data not shown), implying that TMPRSS4 contributes to CSC functions through various molecular mechanisms depending on the cellular context." (PMID 34809669, 2021).
pancreatic cancer (16 papers, 2013 to 2025). "Clinically, increased TMPRSS4 expression displayed the potential diagnostic efficiency for pancreatic carcinoma (AUC = 0.91), which was associated with adverse clinical outcome." (PMID 36380313, 2022). "In this study, we unraveled that overexpression of TMPRSS4 is associated with poor prognosis in pancreatic cancer." (PMID 33816264, 2021). "In total TCGA pancreatic cancer, TMPRSS4 expression is associated with prognosis." (PMID 33816264, 2021). "However, the underlying molecular mechanisms of TMPRSS4 in pancreatic cancer development and progression remain unclear." (PMID 33816264, 2021). "TMPRSS4 shows high clinical potential in various malignancies including pancreatic cancer and is under consideration as a novel oncogenic therapeutic target." (PMID 35359382, 2022). "Abundant evidence revealed that TMPRSS4 played an oncogenic role in various types of cancer, including pancreatic carcinoma, breast cancer, gastric cancer, lung cancer, prostate cancer, liver cancer colon cancer, and TC." (PMID 36380313, 2022). "TMPRSS4 expression was markedly upregulated in pancreatic cancer tissue as compared to the normal pancreatic tissue." (PMID 33816264, 2021). "Taken together, these results further validate the fact that the activation of the ERK1/2 signaling pathway affects the functional outcome of TMPRSS4, that is, promotes cell proliferation and inhibits apoptosis in pancreatic cancer." (PMID 33816264, 2021). "Transmembrane protease serine 4 (TMPRSS4) is upregulated in various kinds of human cancers, including pancreatic cancer." (PMID 33816264, 2021). "We then further explored the relationship between TMPRSS4 expression and prognosis in all 177 pancreatic cancer patients in the TCGA dataset, and found that they were negatively correlated and TCGA dataset." (PMID 33816264, 2021). "The percentage of apoptotic cells was significantly higher in siTMPRSS4 pancreatic cancer cells than in the control cells but lower in the TMPRSS4 overexpressing cells." (PMID 33816264, 2021). "The EdU and CCK-8 assays were performed and the results indicated a significant decrease in cell proliferation in the pancreatic cancer cells with reduced TMPRSS4 expression." (PMID 33816264, 2021). "Cox univariable and multivariable analysis of clinicopathological variables and TMPRSS4 expression in relation to OS in pancreatic cancer patients." (PMID 33816264, 2021). "In pancreatic cancer TMPRSS4 is overexpressed and involved in metastasis formation and tumor invasion." (PMID 33816264, 2021). "We also found that TMPRSS4 mediates cell proliferation and inhibits apoptosis in pancreatic cancer cells." (PMID 33816264, 2021). "In pancreatic carcinoma, TMPRSS4 is identified as a candidate biomarker by affecting the clonability and invasiveness of pancreatic cancer cells, and overexpressed TMPRSS4 predicts poor prognosis." (PMID 32695668, 2020). "Transmembrane protease, serine 4 (TMPRSS4), as a member of TTSPs, was first discovered by differential gene analysis for pancreatic cancer markers." (PMID 23857060, 2013). "Our findings indicate that TMPRSS4 could be a promising prognostic biomarker and a therapeutic target for the treatment of pancreatic cancer." (PMID 33816264, 2021). "Recently, it could be shown that TMPRSS4 promotes cell proliferation in pancreatic cancer cells and inhibits apoptosis by activating the ERK1/2 pathway." (PMID 34281234, 2021). "Further in-depth investigation of TMPRSS4 might lead to its development as an efficient prognostic biomarker and therapeutic target for pancreatic cancer." (PMID 33816264, 2021). "Moreover, analysis of the GSE62452 dataset revealed that TMPRSS4 overexpression is correlated with poor prognosis in pancreatic cancer." (PMID 33816264, 2021). "Importantly, the outcome of this study revealed the critical role of TMPRSS4 in mediating cell proliferation and apoptosis in pancreatic cancer cells via the ERK1/2 signaling pathway." (PMID 33816264, 2021).